RNF148 (ring finger protein 148)
Synonyms: MGC35222
Tractability: Antibody: UniProt predicts a signal peptide or a membrane-spanning region. PROTAC: ubiquitination databases record sites on it.
Gene: Protein-coding gene on chromosome 7 (122,701,668 to 122,702,922, reverse strand). Ensembl gene ENSG00000235631.
Subcellular location: Membrane
Subcellular location (Human Protein Atlas): Cytosol
Gene Ontology:
Molecular function: ubiquitin protein ligase activity; ubiquitin-protein transferase activity
Biological process: ubiquitin-dependent protein catabolic process
Cellular component: endoplasmic reticulum; Golgi apparatus; late endosome; membrane
Genetic constraint (gnomAD): Loss-of-function variants: 16 observed, 21.32 expected, observed/expected ratio (o/e) 0.75, 90% interval 0.51 to 1.14. The upper end of that interval is the gene's LOEUF score, 1.14, which puts it in group 4 of 6, group 1 being the genes least tolerant of losing a copy. Missense variants: 418 observed, 386.68 expected, observed/expected ratio (o/e) 1.08, 90% interval 1 to 1.17. Synonymous variants: 147 observed, 141.16 expected, observed/expected ratio (o/e) 1.04, 90% interval 0.91 to 1.19.
Homologues: Orthologues: mouse Rnf148 (81% identical). Paralogues in human: RNF133 (55% identical), RNF128 (50% identical), RNF149 (36% identical), RNF150 (36% identical), RNF130 (34% identical), RNF13 (21% identical), ZNRF4 (19% identical), RNF167 (18% identical), RNF215 (16% identical).
Diseases named in the same sentence as RNF148 in open-access papers:
RNF148 is named in the same sentence as 1 disease in open-access papers, as found by Europe PMC text mining. Sharing a sentence is not in itself a finding about the gene and the disease.
RNF148 shares sentences with these, for which no sentence is quoted: colorectal cancer (1 paper).